ROR1 (ROR family WNT receptor 1)
Description:
Has very low kinase activity in vitro and is unlikely to function as a tyrosine kinase in vivo. Receptor for ligand WNT5A which activates downstream NFkB signaling pathway and may result in the inhibition of WNT3A-mediated signaling. In the inner ear, crucial for spiral ganglion neurons to innervate auditory hair cells. Via IGFBP5 ligand, forms a complex with ERBB2 to enhance CREB oncogenic signaling.
Synonyms: NTRKR1; dJ537F10.1
Tractability: Small molecule: a structure with a bound ligand is known; it belongs to a druggable protein family. Antibody: a drug acting on it is in phase 2 or 3 trials; its Gene Ontology location is reachable by antibodies, with high confidence; UniProt predicts a signal peptide or a membrane-spanning region. PROTAC: ubiquitination databases record sites on it.
Gene: Protein-coding gene on chromosome 1 (63,774,017 to 64,181,498, forward strand). Ensembl gene ENSG00000185483.
Subcellular location: Cell membrane; Cell projection, axon
Pathways (Reactome):
Signal Transduction: WNT5A-dependent internalization of FZD2, FZD5 and ROR2
Gene Ontology:
Molecular function: ATP binding; protein binding; signaling receptor activity; Wnt receptor activity; Wnt-protein binding; coreceptor activity; transmembrane receptor protein tyrosine kinase activity; protein kinase activity
Biological process: cell population proliferation; positive regulation of canonical NF-kappaB signal transduction; sensory perception of sound; cell surface receptor protein tyrosine kinase signaling pathway; inner ear development; Wnt signaling pathway
Cellular component: membrane; plasma membrane; receptor complex; axon; axon terminus; cytoplasm
Genetic constraint (gnomAD): Loss-of-function variants: 16 observed, 74.47 expected, observed/expected ratio (o/e) 0.21, 90% interval 0.14 to 0.33. The upper end of that interval is the gene's LOEUF score, 0.33, which puts it in group 1 of 6, group 1 being the genes least tolerant of losing a copy. Missense variants: 891 observed, 1,188.3 expected, observed/expected ratio (o/e) 0.75, 90% interval 0.71 to 0.79. Synonymous variants: 375 observed, 432.91 expected, observed/expected ratio (o/e) 0.87, 90% interval 0.8 to 0.94.
Gene-disease validity (ClinGen):
ClinGen rates the evidence that ROR1 causes each of these diseases.
nonsyndromic genetic hearing loss (autosomal recessive): Limited. A disease characterized by hearing loss that is not part of a larger syndrome.
Homologues: Orthologues: macaque ROR1 (99% identical), pig ROR1 (98% identical), chimpanzee ROR1 (97% identical), mouse Ror1 (97% identical), rat Ror1 (97% identical), dog ROR1 (96% identical), rabbit ROR1 (95% identical), guinea pig ROR1 (94% identical), tropical clawed frog ror1 (86% identical), zebrafish ror1 (74% identical). Paralogues in human: ROR2 (57% identical), NTRK2 (22% identical), MUSK (22% identical), NTRK1 (21% identical), ROS1 (21% identical), NTRK3 (20% identical), INSR (19% identical), IGF1R (18% identical), ALK (18% identical), EPHA6 (18% identical), EPHB1 (18% identical), EPHB3 (18% identical), and 41 more.
Diseases named in the same sentence as ROR1 in open-access papers:
ROR1 is named in the same sentence as 147 diseases in open-access papers, as found by Europe PMC text mining. Sharing a sentence is not in itself a finding about the gene and the disease. The quoted sentences say what the papers report.
breast cancer (100 papers, 2010 to 2026). A primary or metastatic malignant neoplasm involving the breast. "ROR1 has been implicated in cancers such as leukaemia, breast cancer and ovarian cancer as a regulator of tumour cell survival, drug resistance, stemness, and proliferation." (PMID 38689429, 2024). "ROR1-lEVs correlated with EpCAM-lEVs, which have already been established as prognostic and diagnostic biomarkers for breast cancer." (PMID 37430307, 2023). "High-level expression of ROR1 on breast cancer cells has been associated with epithelial–mesenchymal transition (EMT), tumor cell proliferation, and metastases." (PMID 37029329, 2023). "In breast cancer cells, cellular expression of ROR1 and ROR2 has been linked to tumor invasion via Rho/Rock signaling." (PMID 37430307, 2023). "Receptor tyrosine kinase-like orphan receptor 1 (ROR1) is expressed on tumor cells of primary breast cancer and high expression of ROR1 has been associated with poor prognosis." (PMID 36351947, 2022). "Although accumulating evidence has demonstrated that ROR1 is associated with aggressive breast-cancer phenotypes, the whole picture of its biological function remains poorly understood." (PMID 35712490, 2022). "In the case of breast cancer, miR-30a suppresses cell growth, invasion, and metastasis by targeting ROR1, and loss of miR-30a expression causes oncogenesis." (PMID 36276982, 2022). "High ROR1 levels in breast cancer are associated with chemoresistance, metastasis, and poorer outcomes." (PMID 33445713, 2021). "High ROR1 expression has also been found to be associated with stemness and tumor recurrence in ovarian cancer, breast cancer, glioblastoma and chronic lymphocytic leukemia." (PMID 32020017, 2020). "For example, ovarian and breast cancer tumors with high levels of ROR1 were typically poorly differentiated and associated with an aggressive disease stage." (PMID 31382410, 2019). "Here we report that ROR1 associates with cortactin in primary breast-cancer cells or in MCF7 transfected to express ROR1." (PMID 31667337, 2019). "Consistent with this notion are studies demonstrating that high-level expression of ROR1 in breast cancer is associated with increased rates of metastases and poorer survival." (PMID 31667337, 2019). "Immunoblot analysis of anti-cortactin or anti-ARHGEF1 i.p. by using lysates made from ROR1+ breast-cancer PDX cells revealed that ARHGEF1 associated with cortactin, and more specifically Y421-phosphorylated cortactin." (PMID 31667337, 2019). "Previous reports have indicated that high ROR1 expression was associated with metastasis in breast cancer and ovarian cancer." (PMID 28427197, 2017). "Here we show that the neoplastic cells of many human breast cancers express the ROR1 protein and high-level expression of ROR1 in breast adenocarcinoma was associated with aggressive disease." (PMID 22403610, 2012). "We hypothesize that prognostic value also may be observed in stratifying breast cancers with respect to their relative levels of ROR1 and/or ROR2 in the context of residual disease or associated clinical subtype." (PMID 37029329, 2023). "The expression of ROR1 and pCREB was associated with the Ki67 labeling index, pointing to a role for these molecules in tumor cell proliferation, similar to observations in human breast cancer cells." (PMID 36873868, 2023). "Interrogation of tumor biopsies from 122 patients before and after neoadjuvant chemotherapy revealed the expression level of ROR1 was increased in residual breast cancer cells after surgery and was associated with enhanced expression of genes associated with EMT, proliferation, and cancer stemness." (PMID 37029329, 2023). "Using the annotated I-SPY2 transcriptome data from a cohort of nearly 1000 patients with newly diagnosed high-risk early breast cancer, we found that high-level pretreatment expression of ROR1 or ROR2 had a distinct subtype-specific association with adverse risk." (PMID 37029329, 2023).
breast cancer (continued). "Cancer progression is influenced by the EGFR-mediated and Wnt signaling pathways, which are interconnected through the PI3K/AKT/mTOR pathway ROR1 is associated with advancing aggressive phenotypes in breast cancer, including triple-negative breast cancer (TNBC)." (PMID 37779899, 2023). "High ROR1 or high ROR2 was associated with breast cancer subtypes." (PMID 37029329, 2023). "However, ROR1 expression is significantly increased in aggressive breast cancer and is associated with poor clinical outcomes." (PMID 33670942, 2021). "In addition, expression of ROR1 in breast cancer cell lines was associated with the EMT gene expression signature, and silencing of ROR1 inhibited metastasis of tumor xenografts in nude mice." (PMID 30832318, 2019). "Interestingly, both Ror1 and Ror2 have been suggested as receptors for Wnt5a, have been linked to breast cancer progression and their expression was previously observed in breast cancer brain metastasis." (PMID 28695110, 2017). "Conversely, silencing ROR1 in human breast cancer cell lines could attenuate expression of genes associated with EMT and impair their migration/invasion capacity in vitro and their metastatic potential in vivo." (PMID 28491097, 2017). "As such, expression of ROR1 appears associated with aggressive disease in human breast cancer." (PMID 22403610, 2012). "The results presented here indicate that a substantial subset of human breast cancers expresses ROR1 and such expression may be associated with aggressive disease." (PMID 22403610, 2012). "ROR1 expression was evaluated in both hematological malignancies and solid tumors and has been associated with poor outcome and reduced therapeutic responses in several cancers including breast cancer, CLL, colorectal cancer, endometrial cancer, lung adenocarcinoma, melanoma and ovarian cancer." (PMID 39551787, 2024). "Conversely, the inhibition of either ROR1 or YAP1 was sufficient to re-sensitize the HER2+ breast cancer cell line HCC1954 to T-DM1." (PMID 40869147, 2025). "In fact, ROR1 has been established to have prognostic significance in several cancers, including breast cancer, colorectal cancer, chronic lymphocytic leukemia, ovarian cancer, lung cancer, and diffuse large B-cell lymphoma." (PMID 40869147, 2025). "Among others, ROR1 kinase showed an increased expression in TN breast cancer cells in vitro upon dex treatment, and also in metastases compared to primary tumours in in vivo xenografts." (PMID 39905197, 2025). "ROR1 expression is associated with a more aggressive disease progression and increased propensity for metastasis in both HER2+ and HER2− breast cancer." (PMID 40869147, 2025). "Increased expression of ROR1 in breast cancer leads to the development of ABCB1, an ATP-dependent drug efflux pump that increases tumor recurrence and resistance to chemotherapy." (PMID 39755633, 2025). "Over the past decade, the role of ROR1 in cancers has been investigated, particularly in chronic lymphocytic leukemia, breast cancer, ovarian cancer, and NSCLC." (PMID 39849645, 2025). "As another mechanism, Wnt5a induces ROR1 to recruit cortactin to promote breast cancer cell migration and metastasis." (PMID 39905197, 2025). "ROR1 is thought to be an attractive biomarker in breast cancer, primarily for TNBC and its subtypes, and increases metastasis by activating various oncogenic signaling pathways, including PI3K/AKT, Hippo, and MEK/ERK pathways." (PMID 40427627, 2025). "Existing evidence indicates that lncRNA DLEU2 influences biological processes such as EMT and cancer stem cell (CSC) enrichment in breast cancer through the DLEU2/ROR1 axis." (PMID 40443971, 2025). "In breast cancer, inhibiting ROR1 expression increases sensitivity to chemotherapy, decreases stemness, and inhibits CSCs from forming spheres or engrafting in immunodeficient mice." (PMID 40869147, 2025).
breast cancer (continued). "ROR1 signaling is also associated with AKT, BMI-1, Rho-GTPase, Hippo-YAP/TAZ and TGFB signaling and a decrease in metastasis-free survival in breast cancer patients." (PMID 40869147, 2025). "Breast cancer patients with high ROR1 expression are seen to have significantly shorter metastasis-free and overall survival rates compared to those with low ROR1 expression." (PMID 40427627, 2025). "Here we find that lncRNA DLEU2 and ROR1 are specifically upregulated in tumor tissues compared to their normal counterparts in TCGA, PubMed GEO datasets, and samples from archived breast cancer tumor tissues." (PMID 38296962, 2024). "Cirmtuzumab, a monoclonal antibody targeting ROR1, is evaluated in clinical trials regarding chronic lymphocytic leukemia, mantle cell lymphoma and breast cancer." (PMID 38846943, 2024). "Zilovertamab is a humanized monoclonal antibody targeting ROR1, an onco-embryonic antigen expressed by malignant cells of a variety of solid tumors, including breast cancer." (PMID 38408999, 2024). "Stress-induced glucocorticoids intensify the metastatic colonization of breast cancer cells by increasing the expression of receptor tyrosine kinase-like orphan receptor 1 (ROR1) and its ligand WNT5A." (PMID 38831236, 2024). "To date, several studies have reported that ROR1 is expressed in many tumor types, including breast cancer, ovarian cancer, and lung cancer." (PMID 38791952, 2024). "The importance of ROR1 has also been characterized in chronic lymphocytic leukemia, diffuse large B-cell lymphoma, melanoma, ovarian cancer, and breast cancer." (PMID 38213538, 2023). "ROR1 and ROR2 are Type 1 tyrosine kinase-like orphan receptors for Wnt5a that are associated with breast cancer progression." (PMID 37029329, 2023). "This is particularly true as our observations hint towards an important contribution of ROR1 in directing tumor vesicles to future organs of breast cancer metastasis." (PMID 37430307, 2023). "This fits to previous observations which demonstrated that the knockdown of ROR1 in MDA-MB-231 breast cancer cells reduced their metastatic spreading to the liver and the lung in immunocompromised mice." (PMID 37430307, 2023). "High ROR1 or high ROR2 distinctly identified subsets of breast cancer patients with adverse outcomes." (PMID 37029329, 2023). "High expression of ROR1 was associated with EMT and tumor metastasis in breast cancer cells and showed poor prognosis in lung adenocarcinoma." (PMID 37241228, 2023). "Using flow cytometry we detected lEVs carrying ROR1 as well as ROR2 in peripheral blood of breast cancer patients." (PMID 37430307, 2023). "Taken together, these observations indicate that ROR1 on EVs is involved in directing tumor EVs to future sites of breast cancer metastasis in vivo." (PMID 37430307, 2023). "We noted HR- HER2- breast cancers expressed the highest levels of ROR1, followed by cancers with the HR-HER2 + subtype." (PMID 37029329, 2023). "The three antigens separated breast cancer patients from healthy individuals with an AUC of 0.663 (95% CI: 0.504–0.821) for ROR1, 0.732 (95% CI: 0.586–0.878) for ROR2 and 0.652 (95% CI 0.489–0.814) for EpCAM." (PMID 37430307, 2023). "Silencing ROR1 has been shown to reduce the spread of metastasis and improve survival rates in breast cancer patients." (PMID 37779899, 2023). "The choice of median cut-point for high- versus low-level expression was based upon our prior study using the median cut-point in analyzing ROR1 expression in breast cancer datasets before and after neoadjuvant treatment." (PMID 37029329, 2023). "When T-cells engineered to express this CAR were co-cultured with the ROR1+ breast cancer cell line MDA-MB-231, they exhibited rapid proliferation, high levels of IFN-γ and IL-2, and the ability to kill the tumor cells." (PMID 36873868, 2023).
breast cancer (continued). "Current clinical trials evaluate targeting of ROR1/2 in breast cancer as a novel therapeutic approach by using CAR-T cells or the monoclonal antibody cirmtuzumab directed against ROR1." (PMID 37430307, 2023). "In breast cancer, increased ROR1 expression induces expression of ATP-dependent drug efflux pumps (ABCB1), resulting in chemotherapy resistance and tumor recurrence." (PMID 35414783, 2022). "In breast cancers, increased expression of Ror1 can be attributable to reduced expression of miR30a, a suppressor of Ror1, which is up-regulated by aging, and age-related up-regulation of miR30a induces cellular senescence." (PMID 35493090, 2022). "It has also been shown in an independent study that ROR1 activation by WNT5A promotes breast cancer migration and metastasis." (PMID 36107918, 2022). "Particular attention has been paid to the functional and clinical significance of ROR1 in many malignancies, including breast cancer." (PMID 35712490, 2022). "The receptor tyrosine kinase ROR1, a transmembrane glycoprotein, plays an important role in embryogenesis and is overexpressed in many malignant tumors, such as leukemia, breast cancer, prostate cancer, and ovarian cancer." (PMID 36557069, 2022). "Malignancy-associated expression of ROR1 has been observed in B-cell chronic lymphocytic leukemia (B-CLL), mantle cell lymphoma (MCL), breast cancer, and ovarian cancer." (PMID 36483567, 2022). "In vitro, ROR1 expression is associated with TNBC cell lines MDA-MB-231 and MDA-MB-468 but is lowly expressed in MCF7 ER+ breast cancer cell lines." (PMID 33670942, 2021). "ROR1-high compared to ROR1-low breast cancer tumors initially showed high expression of genes typically associated with mesenchymal cells." (PMID 33445713, 2021). "In vivo, metastases derived from ROR1 knockdown breast cancer cells injected into immunodeficient mice showed diminished expression of phosphorylated AKT and CREB." (PMID 33445713, 2021). "Similar observations have been made in breast cancer in which ROR1 knockdown decreased CXCR4 expression resulting in decreased chemotaxis of the cells towards a CXCL12 gradient." (PMID 33445713, 2021). "Comparable to breast cancer, ROR1 was expressed in certain subtypes and was particularly high in lung adenocarcinoma (40–65% positive), while squamous carcinomas stained positive at much lower frequencies." (PMID 33445713, 2021). "In contrast to ROR1, ROR2 was not only found to be highly expressed in basal-like but in 87% of all breast cancers, and high levels were associated with shorter overall survival." (PMID 34911552, 2021). "A previous study has reported that Dex promotes breast cancer metastasis via the Wnt pathway and its downstream gene, tyrosine-protein kinase transmembrane receptor ROR1, which was also upregulated in our study." (PMID 34272474, 2021). "Recently, the elevated levels of stress hormones observed during breast cancer progression were shown to induce glucocorticoid receptor signaling in distant tissues, which resulted in the induction of ROR1." (PMID 33445713, 2021). "In line, combining paclitaxel treatment with ROR1 blockade significantly enhanced tumor growth inhibition in a patient-derived xenograft (PDX) model for breast cancer." (PMID 33445713, 2021). "Altogether, these data suggest ROR1 is enriched in chemoresistant breast cancer tumors and cell lines." (PMID 32020017, 2020). "The ROR1 signaling pathway in breast cancer culminates in apoptosis inhibition, proliferation and metastasis." (PMID 32020017, 2020). "To establish a potential mechanism of ROR1 regulation of drug efficacy in breast cancer cells, we investigated the multi-drug efflux pump ABCB1 after ROR1 inhibition." (PMID 32020017, 2020). "Analysis of breast cancer patient gene expression data from NCBI’s Gene Expression Omnibus (GEO) suggests ROR1 is enriched in patients with poor response to chemotherapy." (PMID 32020017, 2020).